STAT3 (signal transducer and activator of transcription 3)
Diseases named in the same sentence as STAT3 in open-access papers (continued):
Sharing a sentence is not in itself a finding about the gene and the disease.
breast cancer (continued). "SOCS2 is hypermethylated in ovarian and breast cancers, in which its reduced expression is associated with the activation of STAT3, indicating an increased cytokine responsiveness in these tumors." (PMID 24280133, 2014). "Previous studies have shown that STAT3 is a key regulator of tumor growth, metastasis and tumor-associated immunosuppression in patients with malignancies such as breast cancer." (PMID 25013518, 2014). "STAT3 has been shown to be associated with proinflammatory responses and is activated in breast cancer tissues." (PMID 24886617, 2014). "We found that human MDA-MB-231 breast cancer cells express the IL-10 receptor and that exposure to cmvIL-10 results in activation of Stat3, a transcription factor strongly associated with enhanced metastatic potential and chemo-resistance." (PMID 24520416, 2014). "Using in vivo claudin-low cell line xenograft models of human breast cancer, a very recent study has directly and functionally linked STAT3 signaling activity to breast TIC cell functions." (PMID 25026286, 2014). "Certainly, in BALB-neuT mice this network seems to be particularly interesting, as in a BALB-neuT mice knock-in for a constitutively active Stat3 allele, we observed an earlier and more invasive onset of mammary tumors." (PMID 25136593, 2014). "Accumulating studies provide strong evidence that the STAT3 activation has been linked with a variety of tumors including multiple myeloma, ovarian cancer, breast cancer, prostate cancer, and so on." (PMID 25180593, 2014). "In particular, the aberrant production of IL-6 and CCL2 in mammary cancer activates STAT3 in CAFs, which finally sustains tumor-associated inflammation and is required for breast cancer cell migration." (PMID 25136593, 2014). "It has been shown that upregulated expression of STAT3 is associated with more malignant behavior of tumor cells and worse prognosis in a variety of human malignancies, e.g., cancers of the breast, prostate, ovary, lung, head and neck, esophagus, and brain." (PMID 24662939, 2014). "Analysis of STAT1 and STAT3 protein expression in a series of 546 breast cancers also indicated that high expression of STAT3 protein was associated with improved survival (DMFS, p = 0.006)." (PMID 24728078, 2014). "Signal transducer and activator of transcription 3 (STAT3) has been implicated in the pathogenesis of a variety of human malignancies, including head and neck cancer, myeloma, prostate cancer, breast cancer, colon cancer, and ovarian cancer." (PMID 23663277, 2013). "In human cancers, including breast cancer, the persistent activation of STAT3 is often associated with tumor progression." (PMID 23326564, 2013). "Sorafenib, SC-1 and SC-43 induced apoptosis in association with downregulation of p-STAT3 and its downstream proteins cyclin D1 and survivin in a dose-dependent manner in breast cancer cell lines (HCC-1937, MDA-MB-468, MDA-MB-231, MDA-MB-453, SK-BR3, MCF-7)." (PMID 23938089, 2013). "We examined the molecular signaling downstream of p-STAT3 in drug-treated breast cancer cells to confirm that p-STAT3 plays a major role in the apoptotic effects caused by SC-1 and SC-43 in breast cancer cells." (PMID 23938089, 2013). "In summary, we have expanded previous knowledge of the role for the ZIP6 gene in zebrafish gastrulation, regulation by oestrogen and STAT3 and association with breast cancers that spread to the lymph nodes." (PMID 23919497, 2013). "The current study suggests that invasion of breast cancer is associated with up-regulation of Rac and STAT3 activity." (PMID 22689141, 2012). "In our study, STAT3 was implicated as a mediator of tamoxifen resistance in breast cancer stem cells." (PMID 23554768, 2012). "Seven members of the STAT family have been cloned (STAT1∼4, 5a, 5b, and 6), among which STAT5a and STAT3 were confirmed to be most strongly associated with the proliferation and oncogenesis of human breast cancer cells." (PMID 23554768, 2012).
breast cancer (continued). "Targeting pSTAT3 has becoming an important strategy for cancer therapies since hyper-phosphorylation of STAT3 at tyrosine residues is associated with various types of human cancers including breast cancer." (PMID 22394684, 2012). "Specifically, elevated levels of phosphorylated Stat3 in tumor samples from 45 patients with high-risk breast cancer was correlated with an incomplete response to neo-adjuvant chemotherapy (i.e. poor prognostic feature)." (PMID 22140473, 2011). "Src and signaling molecules downstream of Src, including signal transducer and activator of transcription 3 (Stat3) and cMyc, have been implicated in the development, maintenance and/or progression of several types of human cancers, including breast cancer." (PMID 21541295, 2011). "MSCs carrying Adv-Stat3(-) caused viral amplification, depletion of Stat3 and its downstream proteins, and led to significant apoptosis in breast cancer and melanoma cell lines." (PMID 22054049, 2011). "In breast cancer, miR-155 overexpression has been linked to increased proliferation and constitutive activation of signal transducer and activator of transcription 3 as well as cell survival and chemoresistance through FOXO3a." (PMID 21863027, 2011). "A recent study and our data uncovered the association of catacholamine with STAT3 activation in ovarian and breast cancer cells." (PMID 20939893, 2010). "A number of different mechanisms responsible for Stat3 activation, including abnormal activation of receptor tyrosine kinases, Src, and Janus kinases (Jaks), have been implicated in breast cancer." (PMID 17531096, 2007). "For example, 15d-PGJ2 has been shown to have potent PPARγ-independent proapoptotic effects on breast cancer cells, which exhibit constitutive Stat3 activation linked to cooperative activity of Src and JAK family tyrosine kinases." (PMID 15316561, 2004). "Together, these results corroborate our hypothesis of a positive association between redox APE1 and STAT3 in breast cancer." (PMID 41090323, 2025). "STAT3 is activated in about 70% of breast cancers but is most often associated with TNBC." (PMID 40507264, 2025). "In addition, we verified the association between APE1 and STAT3 in breast cancer patient samples from TCGA and their relationship with proliferation and metastasis." (PMID 41090323, 2025). "However, inappropriate activation of either STAT3 or STAT5 has been shown to play a role in breast cancer, where STAT3 is highly associated with aggressive tumors and STAT5 is associated with lower-grade and more differentiated tumors." (PMID 40507264, 2025). "Similarly, STAT3 activation has been implicated in the progression of breast cancer, while RAB5A expression is upregulated in an m6A-YTHDF2-dependent manner by ALKBH5, promoting colorectal cancer development." (PMID 40959079, 2025). "STAT3 has been implicated in resistance to lapatinib in HER2+ breast cancer." (PMID 39191139, 2024). "STAT3 has been implicated in a number of cancers, including OS, where overexpression is often seen in cases with worse outcomes, with an exception being breast cancer." (PMID 39570878, 2024). "Meanwhile, IL-6, and its associated STAT3 signaling, has recently gained attention as an inflammatory cytokine facilitating the formation of a (pre)metastatic niche for solid malignancies, including breast cancer." (PMID 39128004, 2024). "Similarly, the activation of the PI3K, Stat3, and Ras signaling pathways has been associated with different subtypes of breast cancer." (PMID 38791246, 2024). "STAT3 is also implicated in VEGFC/VEGFR3 signaling during breast cancer." (PMID 38218743, 2024). "Here, to follow up on observations showing that PD-L1 is N-linked glycosylated in breast cancer patient samples, it is important to validate the connections between the STAT3 and STAT1 proteins with the N-linked glycosylation status of PD-L1 in breast cancer patients and in mice tumor samples." (PMID 37830552, 2023).
breast cancer (continued). "Moreover, in breast cancer, a poor response to radiotherapy was associated with IL-6 and p-STAT3 expression." (PMID 36635302, 2023). "In their study, breast cancer cell lines were more sensitive to paclitaxel when B7-H3 was silenced which may be associated with the prevention of the activation of the Jak2/Stat3 pathway." (PMID 36859240, 2023). "The IL6/STAT3 pathway is aberrantly hyperactivated in breast cancer, is linked to poor prognosis in patients, and may drive mammary tumorigenesis in SI rats." (PMID 36980301, 2023). "In addition, the STAT3 pathway also associates with different features of oncogenesis in breast cancer, including metastasis, higher stages of disease progression, and Pal resistance." (PMID 37752122, 2023). "Elevated expression of STAT3 (especially its phosphorylated form, pSTAT3) in PCa, similarly to most investigated solid tumors, was found to be associated with poor prognosis, with the exception of a better prognosis found only in the case of breast cancer." (PMID 37371647, 2023). "Finally, STAT3 control of angiogenesis is associated with c-Src/FAK regulation in ER+ breast cancer cells." (PMID 37896150, 2023). "The preceding analysis suggests a transcriptomic pattern downstream of FAM3C/LIFR/STAT3 modulation that is specifically implicated in mammary carcinoma pathology and that is exemplified by changes in the regulation of an established mediator of EMT and cell fate, TWIST1." (PMID 37927213, 2023). "However, a high p-STAT3 expression was significantly associated with a poor prognosis in ER(−) breast cancer, particularly TNBC." (PMID 35314590, 2022). "Much previous evidence supports the role of HER2 in RT resistance, and HER2+/CD44+/CD24−/low cells, Fak activation in vitro and in vivo, and STAT3-survivin signaling may be associated with RT resistance in HER2+ breast cancer patients." (PMID 36686782, 2022). "In addition to the critical roles of IL-6/JAK/STAT3 signaling in breast cancer, hyperactivation of this pathway has also been implicated in suppressing anti-tumor immune responses in tumor microenvironment." (PMID 35924148, 2022). "The cytokine interleukin-6 (IL6) and its downstream effector STAT3 form a major oncogenic pathway in breast cancer that has been hypothesized to be functionally linked to estrogen receptor (ER)." (PMID 36056349, 2022). "Interestingly, these effects were reversed once they blocked the actions of epidermal growth factor receptors (EGFR), suggesting that BPA’s association with breast cancer is dependent on STAT3 signaling." (PMID 35955412, 2022). "Moreover, STAT3 signaling activation induces survivin gene expression, which leads to resistance to apoptosis in cells associated with breast cancer in humans." (PMID 36080130, 2022). "Furthermore, miR-146b inhibits NF-κB-mediated production of IL-6, a proinflammatory cytokine associated with cancer, STAT3 activity, and IL-6/STAT3-driven breast cancer cells migration and invasion." (PMID 36359024, 2022). "As an Food and Drug Administration–approved compound, pyrimethamine is already being tested in the clinic and has shown activity in the treatment of several STAT3-driven malignancies, including chronic lymphocytic leukemia, breast cancer, and intermediate-risk to high-risk myelodysplastic syndrome." (PMID 34953855, 2022). "Notably, the upregulation of miR-17-5p has enhanced the sensitivity of breast cancer cells to paclitaxel-associated cell apoptosis through the modulation of STAT3." (PMID 34804971, 2021). "FER tyrosine kinase increases NF-κβ activation and signals interleukin-6 (IL-6) to regulate STAT3 phosphorylation, which may explain its relationship with breast cancer risk through adiponectin and obesity." (PMID 34367982, 2021). "In a Myc-dependent breast cancer mouse model, STAT3 deficiency was associated with enhanced epithelial-to-mesenchymal transition and metastasis, indicating a potential anti-metastatic property of STAT3." (PMID 34047814, 2021).
breast cancer (continued). "In breast cancer, STAT3 activation is associated with tamoxifen resistance." (PMID 33806019, 2021). "STAT3 overexpression is closely associated with breast cancer development." (PMID 34833950, 2021). "Moreover, increased intercellular STAT3 in Tregs resulted in enhanced proliferation and suppressive functions of Tregs, further supporting the STAT3-associated Tregs immunosuppression in TME of breast cancer." (PMID 33957948, 2021). "STAT3 downregulation is a desirable outcome in cancer cells, as this transcription factor regulates inflammatory and metastatic pathways, has been associated with immune evasion and is a therapeutic target for breast cancer." (PMID 33924764, 2021). "Constitutively activated STAT3 is associated with tumorigenesis and progression of many cancers, such as haematopoietic tumours (eg, multiple myeloma and leukaemia) and solid tumours (eg, breast cancer, lung cancer and pancreatic cancer)." (PMID 33382511, 2021). "Overexpressed vascular endothelial growth factor A (VEGFA) and phosphorylated signal transducer and activator of transcription 3 (P-STAT3) cause unrestricted tumor growth and angiogenesis of breast cancer (BRCA), especially triple-negative breast cancer (TNBC)." (PMID 34059068, 2021). "We found that the expression of p-STAT3 was enhanced according to exposure time of tamoxifen in T47D cells, suggesting the association between STAT3 activation and tamoxifen resistance in HR-positive breast cancer cells." (PMID 34407787, 2021). "Studies of the STAT3-deficient prostate cancer cell line PC-3 (PC3) along with STAT3-proficient breast cancer cell lines (MDA-MB-231, SUM149) revealed that Stattic attenuated histone acetylation and neutralized effects of the histone deacetylase (HDAC) inhibitor romidepsin." (PMID 33839684, 2021). "Additionally, we show that TrkA interacts with and phosphorylates STAT3 on its Y705 residue, inducing oncogenic gene transcription to support breast cancer cell stemness, and that loss of Y705 residue abrogates STAT3 interaction with TrkA." (PMID 34066153, 2021). "However, because transient silencing of gene expression rarely eliminates its target completely, we next compared genetically STAT3-deficient PC3 prostate cancer cells and the STAT3-proficient MDA-MB-231 breast cancer cells." (PMID 33839684, 2021). "STAT3 plays a central role in tumorigenesis, but to the best of the authors' knowledge, no studies have investigated the association between levels of pSTAT3 and lifestyle factors in breast cancer." (PMID 32850390, 2020). "In addition, researchers have found that ~70% of breast cancers exhibit constitutive activation of STAT3, and STAT3 has been strongly associated with TNBC." (PMID 32328465, 2020). "It has been reported that STAT3 and p-STAT3 expression is associated with worse overall survival of many malignancies, including lung cancer, gastric cancer and hepatic cancer, but better prognosis of breast cancer." (PMID 32194797, 2020). "Therefore, in the current study, we performed an integrated analysis of lncRNAs which are dysregulated in breast cancer cells, and found that linc00514/STAT3/Jagged1 axis is associated with the breast cancer tumorigenicity and macrophage M2 polarization." (PMID 32943090, 2020). "Therefore, targeting the IL-6/JAK/STAT3 pathway can be considered as an effective therapeutic approach for cancers associated with overexpression of IL-6, including breast cancer." (PMID 32847008, 2020). "Apoptotic cell death was observed by treating MDA-MB-231 human breast cancer cells with STAT3-siRNA or inhibiting STAT3, for example, decreased phosphorylation of STAT3 by hydrazinocurcumin was associated with down-regulations of the expressions anti-apoptotic and metastasis-enhancing factors." (PMID 32340377, 2020). "STAT3 is also widely implicated in drug resistance in different breast cancer subtypes." (PMID 33266219, 2020). "The JAK2/STAT3 axis has been implicated in the enhanced breast cancer cell metastasis." (PMID 31315632, 2019).
breast cancer (continued). "For instance, loss of PTEN in a HER2-overexpression genetic background or the trastuzumab resistance in breast cancer cells has been linked to activation of the IL-6/STAT-3/NF-κB inflammatory loop, which induced an EMT phenotype and expansion of the CSC population." (PMID 31417869, 2019). "Bergamottin treatment of MDA-MB-231 breast cancer proliferation has caused a significant reduction of phosphorylation, nuclear translocation, expression, and DNA binding activity of signal transducers and activator of transcription 3 (STAT3)." (PMID 31181737, 2019). "Consistently with the in vitro data, progranulin expression specifically correlated with enhanced STAT3 transcriptional activity in the presence of activated STAT3 in primary breast cancer samples and was associated with reduced overall survival in breast cancer patients." (PMID 29914167, 2018). "Additionally, the Src/ANXA2/STAT3 pathway has been implicated in breast cancer invasion and metastasis formation." (PMID 30050103, 2018). "Notably, STAT3 was already identified as a dormancy-associated gene in estrogen receptor, ER-positive breast cancer cells." (PMID 30231553, 2018). "Therefore, additional evidence is necessary to verify the association between STAT3 activation and OS in different breast cancer subtypes." (PMID 29560131, 2018). "Subgroup analysis showed that elevated STAT3 expression was associated with poor prognosis of gastric cancer, lung cancer, gliomas, hepatic cancer, osteosarcoma, prostate cancer, pancreatic cancer but better prognosis of breast cancer." (PMID 26959884, 2016). "STAT3 showed a less significant association with overall breast cancer risk (p value = 0.033)." (PMID 26621531, 2016). "Our comprehensive examination of associations between polymorphisms in the immunosuppression pathway genes and breast cancer risk revealed that STAT3, IL5, and GM-CSF may play a role in overall breast cancer susceptibility among women of European ancestry." (PMID 26621531, 2016). "Aberrant STAT3 signaling has been associated with breast cancer." (PMID 26768588, 2016). "Additionally, the JAK2/STAT3/IL6 pathway has been shown to be required for the growth of CD44-CD24+ breast cancer cells, cell surface markers believed to be associated with breast TICs." (PMID 27764181, 2016). "We showed that AF1q is associated with STAT3 signaling in breast cancer cells." (PMID 27259262, 2016). "Interestingly, STAT3 overexpression was associated with favorable 3-year OS of breast cancer (OR = 0.51, 95% CI = 0.35 to 0.74, P = 0.0004)." (PMID 26959884, 2016). "Importantly, the IL-6/STAT3/NF-κB pro-inflammatory circuit was also active in cancer-associated fibroblasts isolated from breast cancer patients." (PMID 27248826, 2016). "And STAT3 overexpression in breast cancer tissue is associated with favorable OS." (PMID 26959884, 2016). "Our data suggested that some factors secreted by ES cells could efficiently suppress the Stat3 pathway in breast cancer, resulting in a loss of tumorigenicity." (PMID 27460364, 2016). "Through a chemical genetic screen and a suite of drug mechanism-of-action studies, we here identify SYK-dependent STAT3 activation as a novel critical vulnerability of basal-like breast cancer cells, next to AURKA, which was previously implicated to be a potential target in BLBC." (PMID 25699542, 2015). "Taken together, our findings indicate that blocking Stat3 activity with WP1066 may have promise in the treatment of brain metastasis of breast cancer through targeting both tumor cells and tumor-associated endothelial cells." (PMID 25881542, 2015). "Numerous publications have provided evidence that the STAT3 gene produces oncogenic effects in a variety of cancers, including being active in 50–60% of primary breast tumours and being linked to the promotion of breast cancer stem cell traits." (PMID 26097876, 2015).